AR (androgen receptor)
Diseases named in the same sentence as AR in open-access papers (continued):
Sharing a sentence is not in itself a finding about the gene and the disease.
cancer (continued). "Specifically, genes at AR sites specific to mature differentiated tissue (LiT genes) and genes at AR sites specific to de-differentiated late-stage cancer (GiM genes) were most prominently associated with outcome." (PMID 35509021, 2022). "The linkage of USP13 to these PCa-related signaling pathways uncovers the underlying mechanisms of USP13 in cancers and provides solid evidence to support its role in facilitating AR activity." (PMID 36564767, 2022). "These alterations cause AR signaling to reactivate and promote cancer cell proliferation even in the presence of secondary antiandrogens, such as enzalutamide or apalutamide." (PMID 36050295, 2022). "For 8 decades, AR has served as the major therapeutic target for the systemic treatment of metastatic CaP, which causes more than 30,000 cancer deaths in American men each year." (PMID 35326387, 2022). "HOXB13, like FOXA1, is a pioneer transcription factor involved in establishing a cancer-associated AR cistrome." (PMID 36212399, 2022). "Although MUTYH is considered an AR predisposition gene, several studies also suggest a modestly increased cancer risk for heterozygous mutation carriers." (PMID 35739278, 2022). "A total of 101 (51.3%) of all cancer patients had a p.H875Y mutation in the androgen receptor gene (AR, COSM238555)." (PMID 35053623, 2022). "The AR has been implicated in Epithelial–Mesenchymal Transition (EMT) regulation in the early literature on cancer." (PMID 36430245, 2022). "Still, the underlying mechanisms of the involvement of AR p.H875Y mutation in the carcinogenesis of these cancer types should be investigated." (PMID 35053623, 2022). "Methylation of melanoma associated antigen 11 (MAGEA11) which was a co-activator of AR was related to poor prognosis of cancer." (PMID 35886904, 2022). "Continued expression of androgen receptor (AR) and its variants such as AR-V7 despite AR-targeted therapy contributes to treatment resistance and cancer progression in advanced CRPC patients." (PMID 34272475, 2021). "An androgen receptor-derived stapled peptide, which disrupts the androgen receptor/filamin A complex assembly, abolishes the androgen-dependent migration and invasiveness of cancer associated fibroblasts." (PMID 33500395, 2021). "Our results also suggest that in TNBCs with AR loss, CNAs affect miRNA expression levels and their corresponding involvement in signaling pathways associated with cancer aggressiveness and patient outcomes." (PMID 34768979, 2021). "NANOG has been implicated in the acquisition of cancer therapy resistance, and its overexpression in PC cells has been shown to reduce AR levels." (PMID 34948357, 2021). "Initiation: Mutations, loss of alleles in the AR gene, and alteration of mRNA sequences are of high importance for the development of this type of cancer." (PMID 33919565, 2021). "Androgen enhances both these effects through androgen receptor/filamin A complex assembly in cancer-associated fibroblasts." (PMID 33500395, 2021). "AR (gene: AR, androgen receptor), a transcriptional regulator involved in many cellular functions, has been proven to be strongly associated with cancer development and patient survival." (PMID 33842538, 2021). "The first targeted multiple entities of critical importance in PC pathobiology, such as AR (with its V7 variant), the Mnk1/2 pathway or the epithelial-mesenchymal transition, while the latter appeared to target the cancer stem cell population." (PMID 34638876, 2021). "In BC and PC, many of the TRIM proteins act independently of AR or ERα and have been associated with regulator functions for central cancer-related pathways including EMT or apoptosis." (PMID 34208621, 2021). "Studies to shed light on the cellular heterogeneity of TME using accurate TME-mimicking cancer organoid models and patient-derived organoids will be needed to elucidate more mechanisms underlying AR protein degradation and antiandrogen resistance in PCSCs." (PMID 34948357, 2021).
cancer (continued). "High overall male cancer risk naturally suggests that AR and testosterone accelerate cancer initiation, progression, or metastasis." (PMID 34768683, 2021). "A specific PIK3CA mutation in kinase domain causes higher expression of AR in cancer cells, both in cells with full SR expression and ER, PR deficient." (PMID 34638264, 2021). "Some of our enrichment results were consistent with the findings validated in other published literatures, where the expression of the lncRNAs were linked to cancer-related processes such as E2F, c-Myc, androgen receptor and oestrogen receptor." (PMID 34872564, 2021). "The karyotype of the LNCaP cells is highly aneuploid, more reminiscent of CRPC than that of a primary cancer still treatable with androgen receptor inhibitors (2790 exome mutations in LNCaP vs. 16–33 in primary cancer hormone-naïve biopsy exomes)." (PMID 33477370, 2021). "Molecular features associated with surviving cancer cells in CRPC included upregulated aberrant-AR, and phosphorylated S6 and proline-rich Akt substrate of 40 kDa (PRAS40)." (PMID 34439133, 2021). "Despite the loss of AR expression, they retained a high proportion of Ki67+ cells while remaining a high-grade carcinoma histologically in vivo (bottom)." (PMID 33724955, 2021). "Binding of AR results in the activation of diverse signaling pathways, including multiple signaling pathways that have been implicated in cancer, including the PI3K/AKT pathway." (PMID 33062889, 2020). "Data on YAP1 and AR expression from 7,971 cancers showed a significant association between AR expression and cytoplasmic and nuclear YAP1 staining." (PMID 32488048, 2020). "Resistance to androgen-receptor (AR) directed therapies is, among other factors, associated with Myc transcription factors that are involved in development and progression of many cancers." (PMID 33167327, 2020). "Expression of this male hormone receptor in these cancers arise from AR gene dysregulation, including mutation, amplification, and alternative splicing." (PMID 32867793, 2020). "We further found that reduced AR mRNA expression was associated with high cancer risk and extrathyroidal extension in patients in PTC." (PMID 32365531, 2020). "These suggested increased risk, with Gleason 5 + 5 and the discovery of a mutation in AR that has been associated with increased cancer cell proliferation and poor outcome." (PMID 32843649, 2020). "In triple-negative FMCs also, AR overexpression was associated with longer disease-free interval (HR = 0.49, 95% CI: 0.28–0.85; p = 0.037) and cancer-specific survival (HR = 0.53, 95% CI: 0.32–0.89; p = 0.046)." (PMID 31888566, 2019). "This enhancer region was found to be amplified in 87% of cancer metastatic samples, in association with an amplified copy of AR gene; importantly, this enhancer region was found to be amplified in only 2% of primary tumors." (PMID 31366128, 2019). "In luminal FMCs as well, AR overexpression was associated with favorable outcome in terms of cancer-specific survival (HR = 0.38, 95% CI: 0.19–0.74; p = 0.017) and overall survival (HR = 0.46, 95% CI: 0.25–0.82, p = 0.024)." (PMID 31888566, 2019). "Although BMP signalling is implicated in mammalian prostate development and cancer growth and metastasis, steroid signalling through the androgen receptor (AR) is thought to be the central regulator of these processes and prostate hyperplasia." (PMID 31589603, 2019). "HNRNPA1 regulated AS of the androgen receptor (AR) and gave rise to a splice variant AR-V7, which conferred drug resistance toward enzalutamide in cancer cells." (PMID 31355251, 2019). "Subsequent experiments in mice with prostate PTEN deletion (Ptenloxp/loxp) clearly demonstrated that castrate-resistant cancer developed in regions of the prostate with simultaneous loss of AR expression." (PMID 31182131, 2019). "Cancer Associated Fibroblasts (CAFs), for example, express a classic AR, mostly confined in the extra-nuclear portion of the cell." (PMID 31616657, 2019).
cancer (continued). "In this study, we discovered a preference in AR expression in serous subtype EOC which causes the promotion of cancer growth." (PMID 30986993, 2019). "It is apparent that by 72 h post-transfection there is notable loss of AR protein in both cancer cells, although it is more prominent in C4-2 than in LNCaP cells." (PMID 31197122, 2019). "PCA3 (prostate cancer-associated 3) is a prostate-specific lncRNA that is involved in the control of cell survival, via the modulation of androgen receptor (AR) signaling." (PMID 31467637, 2019). "BAP1 expression was further linked to androgen receptor (AR) expression: Only 2% of AR-negative, but 33% of strongly AR expressing cancers had strong BAP1 expression (p<0.0001)." (PMID 31903168, 2019). "In cancer, however, a permanent response to drug treatments such as AR gene amplification/mutation or DHFR amplification in response to methotrexate cannot be undone when the treatment is withdrawn, or a compensation pathway is activated in the cancer cells." (PMID 31108832, 2019). "First, the most common AR-modification is an AR splice variant (AR-V7) that renders cancer cells resistant to otherwise effective therapy (e.g. abiraterone and enzalutamide)." (PMID 31289619, 2019). "The hTERT myofibroblasts we used are representative of cancer-associated fibroblasts (CAFs) and the PShTert-AR line has been shown to have a similar AR binding profile, and gene regulation, as primary fibroblasts and in vivo stroma." (PMID 29721186, 2018). "Both cancer-associated events and the normal physiology of prostate involve signaling through the androgen receptor (AR)." (PMID 30305041, 2018). "The pharmaceutical industries have developed a number of selective androgen receptor modulators to target AR in muscle as a therapy for age-related or cancer-related loss of muscle function." (PMID 30360364, 2018). "Along with SPOP-mutant cancers, FOXA1-mutant cancers have been associated with the highest levels of AR transcriptional activity." (PMID 29581876, 2018). "This strategy identified seven AR variant‐regulated genes that also enhance AR activity and drive cancer progression." (PMID 30108134, 2018). "In a separate study, AR-depleted cancer associated fibroblasts (CAFs) promoted increased stem cell marker expression in human PCa cells, apparently via increased levels of Interferon gamma (IFN-γ) and macrophage colony-stimulating factor (M-CSF)." (PMID 29210989, 2017). "Two more lncRNAs regulated by the androgen–AR-axis are the Downregulated RNA in cancer (DRAIC) and the Prostate cancer-associated transcript 29 (PCAT29)." (PMID 28241429, 2017). "ARv567es is a further cancer-associated AR splice form observed in patients and also encodes a constitutively active AR protein." (PMID 28382513, 2017). "Loss of heterozygosity at the AR locus was identified in muscle-invasive tumors and concurrent lesions of carcinoma in situ from female patients." (PMID 28241422, 2017). "There is a clear need for a more contemporary analysis of cancer cells associated with high and low stromal AR content, and to track mutational and transcription events within each compartment." (PMID 28117763, 2017). "ETS1 was known to activate AR, as well as multiple cancer-associated pathways, which resulted in enhanced energy metabolism, cancer cell growth and survival." (PMID 28264478, 2017). "MYST2 has been linked to cancer by way of its role in replication and also through is interaction with the androgen receptor and tumour suppressors ING4 and ING51." (PMID 28811661, 2017). "Multivariate regression analysis found AR transcript levels were independently associated with cancer specific survival." (PMID 28085048, 2017). "In mice, the expression of AR variant isoforms can be sufficient themselves to induce cancer development." (PMID 28382513, 2017).
cancer (continued). "Here, we review the recent advances that demonstrate the presence and involvement of the androgen receptor (AR) in both normal stem cells and cancer stem cells (CSCs), particularly those associated with the prostate." (PMID 26880966, 2016). "Loss or gain of AR function has been implicated in cancers arising from other AR-expressing tissues." (PMID 26814892, 2016). "CREB, responding to hormonal stimulation of the cAMP pathway, is associated with AR in cancer cells." (PMID 26924343, 2016). "Loss or gain of AR function has been implicated in cancers arising from AR-expressing tissues, including RCC." (PMID 26814892, 2016). "To identify genes that are associated with SE progression and androgen/AR signal, we first compared gene expression profiles of cancer tissues from SE patients and matched normal adjacent tissues." (PMID 27144435, 2016). "The resulting CRPC is difficult to eradicate, as these cancer cells mutate to restore AR signaling or progress independently of AR." (PMID 27223260, 2016). "But, more recent clinical evidence associates overexpression of AR with loss of sensitivity to standard endocrine adjuvant therapies, hence increased cancer aggressiveness." (PMID 27746764, 2016). "On the other hand, normolipidic diets containing pork fat (7% lard) have cancer-promoting effects (increase in prostatic weight associated with epithelial hyperplasia and increased expression of AR and PPARγ)." (PMID 25912035, 2015). "In their 2014 Cancer Research paper, Thadani-Mulero and colleagues explored how two common AR splice variants, ARv567 and ARv7, responded to treatment with docetaxel." (PMID 26401448, 2015). "Quantitative RNA (q-PCR) measurement of mAR-Va, b, and c confirmed the elevation of isoforms in hormone intact and CRPC Pten deficient cancers with respect to Wt prostates and normalized to AR-FL (**, p<0.01)." (PMID 26196517, 2015). "Higher Gleason score was associated with a higher median AR level in cancer epithelia (p<0.05) and lower AR in cancer-associated stroma (p<0.05)." (PMID 25965833, 2015). "To assess the role of driver genes, we selected AR for functional study since this gene possesses many functions and its dysregulation is associated with cancer." (PMID 26318424, 2015). "The mRNA expression of ERα was much lower than AR in PC cells (1:100 ratio); however, ERα expression in cancer-associated stromal cells was significantly related to cancer-specific survival in men with bone metastatic PC." (PMID 26526623, 2015). "Further functional studies have also provided evidence for a connection between the AR signaling and the reprogramming of cellular metabolism, an emerging hallmark of cancer cell growth and survival under adverse conditions." (PMID 26690121, 2015). "EC patients had an AR alteration rate of more than 5%, including amplification (0.4%) and mutation (5.8%); EC ranked seventh out of all cancers in this regard." (PMID 26397136, 2015). "Median AR levels were similar in malignant and benign epithelia, but were lower in cancer-associated compared to benign stroma (p=4.1 × 10−8)." (PMID 25965833, 2015). "ARv567es, in which exons 5, 6, and 7 are deleted, is an AR variant notably involved in cancer progression." (PMID 25705125, 2015). "Expression of CK18 was also reported to be maintained in cancer cells after castration, in association with loss of AR and appearance of neuroendocrine markers, suggesting clinical utility for this luminal type cytokeratin." (PMID 25857301, 2015). "Nuclear colocalization of GAK with its association partner AR was observed in cancer cells from all of the GAK-positive surgical specimens." (PMID 24971999, 2014). "AR is a nuclear hormone receptor that is linked to various types of cancers, most notoriously prostate cancer." (PMID 25132814, 2014).
cancer (continued). "The response of the cancer cell to “resist” anti-androgens is correlated with mutations in the androgen receptor that render traditional anti-androgen antagonists ineffective or even counter-productive." (PMID 24598693, 2014). "Estrogen receptor alpha (ER), progesterone receptor (PR), and androgen receptor (AR) have been implicated in the pathophysiology of other cancer types." (PMID 25349530, 2014). "Similar to PARP-1-mediated regulation of transcription factor activity, PARP-1 plays a role in regulating three of the sex hormone receptors most commonly linked to cancer: estrogen receptor (ER), progesterone receptor (PR), and androgen receptor (AR)." (PMID 24350055, 2013). "In accordance with previous results, high AR immunostaining in the metastases was associated with shorter cancer-specific survival after metastasis surgery (log-rank = 8.1, P = 0.004, n = 45)." (PMID 24244276, 2013). "The incidences of AR mutations are much higher in advanced stages cancer (10% – 20%) compared to that of initial stages (0% – 4%)." (PMID 26877888, 2013). "Whatever the cause, as AR transcriptional activation is critical to the growth of the cancer, this nuclear receptor offers an effective pharmacological target to treat CRPC patients." (PMID 23781155, 2013). "In summary, our gene expression analysis using a focused cancer-associated gene set supported previous data on AR and uncovered the association of FGFR1 in CRPC." (PMID 21952621, 2011). "The molecular basis of the formation of an androgen-refractory cancer implicates mainly AR mutations, AR gene amplification, and expression of coactivators that enhances the AR action." (PMID 22191056, 2011). "The use of mifepristone has previously been shown to inhibit the growth of LNCaP tumors formed in nude mice through interaction with the androgen receptor (AR) because of a unique AR-T877A mutation that is present in this cancer cell variant." (PMID 20946663, 2010). "In the "CTNNB" (or β-catenin) keyword, both WNT5B (a representative Wnt family protein) and β-catenin are well-known pathways in carcinogenesis; and elevated expression of these molecules have been associated with AR, ER, and cancer progression." (PMID 21134280, 2010). "One of the hallmarks of the DU145 cell line, a representative of androgen depletion-independent cancers, is the loss of androgen receptor." (PMID 19500415, 2009). "By exploiting commercially available pharmacological inhibitors, we demonstrate that in AR-positive CRPC cell lines, combinatory inhibition of KDM1A and KDM7A leads to a loss of AR and the AR-driven transcriptome, which in turn attenuates cancer-promoting cell phenotypes." (PMID 41870972, 2026). "We identified 31 genes significantly associated with AR activity across 33 cancer types." (PMID 41486951, 2026). "Although androgen deprivation is an effective treatment, 20–30% of the cancers become resistant, paradoxically allowing the disease to progress through alternative signaling pathways, including AR mutations, splice variants, and increased production of growth factors." (PMID 40392873, 2025). "A canonical pathway analysis revealed that the AR/AR-V7-independent HSF1–DBC1 cotarget genes were highly enriched in pathways associated with cancer metastasis, including matrisome-related (NABA gene sets), Fanconi, PLK1 and Wnt signaling pathways, compared with HSF1–DBC1-AR/AR-V7 common targets." (PMID 41028522, 2025). "These mutations can convert AR antagonists into AR agonists, thus promoting cancer progression." (PMID 40958880, 2025). "One of the underlying molecular adaptations of the cancer cell is the expression of AR variants that, devoid of their ligand‐binding domain, are transcriptionally active in an androgen and anti‐androgen independent manner and may drive therapy resistance." (PMID 39258426, 2025). "We explored how male sex hormones (mainly testosterone) and the androgen receptor (AR) may influence cancer risk and outcomes." (PMID 41228208, 2025).